ID2 (inhibitor of DNA binding 2)
Diseases named in the same sentence as ID2 in open-access papers (continued):
Sharing a sentence is not in itself a finding about the gene and the disease.
glioma (19 papers, 2017 to 2025). A benign or malignant brain and spinal cord tumor that arises from glial cells (astrocytes, oligodendrocytes, ependymal cells). "Repression of Id2 gene expression in microglia, in vitro, was associated with a reduced capacity for these cells to promote glioma cell migration." (PMID 39019900, 2024). "In contrast, high DYRK1 expression increases ID2 Thr27 phosphorylation, leading to glioma stemness deficiency, which inhibits tumor growth and is more favorable to the prognosis of GBM patients." (PMID 37786890, 2022). "Another study found that DYRK1A and DYRK1B kinases phosphorylate ID2 on threonine 27 (Thr27), leading to HIF2α destabilization, loss of glioma stemness and inhibition of tumour growth." (PMID 34109727, 2021). "In glioma, the increased ID2 expression was closely associated with tumor grades, and correlated with shorter OS time." (PMID 29190891, 2017). "Yet, our investigation reveals that increased ID2 gene expression is linked to the acquisition of a glioma cells-induced tumour-supportive reactive state by microglia, and that microglia, as well as macrophage, in the context of a GB tumour are also associated with a high ID2 gene expression." (PMID 39019900, 2024). "Whole-exosome sequencing has revealed a consistent co-amplification of ID2, a gene implicated in glioma tumorigenesis, suggesting a potential interplay between MYCN and ID2." (PMID 40365336, 2025). "Reduction of microglial Id2 gene expression levels was shown to significantly impair the migration capacity of C6 glioma cancer cells at 24 h using a transwell migration assay." (PMID 39019900, 2024). "ID1, ID2, and ID3 allele deletions in tumors in an in situ model of brain cancer decreased the amount of glioma stem cells, halted tumor growth, and increased the survival time of mice." (PMID 38195969, 2024). "Supporting our findings, the analysis of these TGCA gene expression dataset revealed that ID2 should be considered as an unfavourable prognostic gene whereas ETS2 as a favourable prognostic gene for patients with glioma." (PMID 39019900, 2024). "The inefficient degradation of ID2-S5D and the increased instability of ID2-S5A were independently confirmed by determining their half-life in a different cell line (U251 glioma)." (PMID 35440621, 2022). "For example, a recent study showed that the chemical compound, AK-778-XXMU, is a potent Id2 antagonist that can be used to treat gliomas." (PMID 35983065, 2022). "Studies in glioma cell lines suggest that ID2 interference with VHL activity can deregulate HIF1α expression and promote tumorigenesis in xenograft models." (PMID 29053101, 2017). "Recently, it has been shown that cancer stem cells and glioma aggressiveness are supported by a mechanism based on Id2 and the hypoxia-inducible factor 2α (HIF2α)." (PMID 28122577, 2017). "Interestingly, ID2 is also overexpressed in H3K27M-mutant gliomas, suggesting a converging oncogenic pathway among these different subgroups." (PMID 40365336, 2025). "Here, we report the identification in vitro of an ID2 (corepressor)-ETS2 (transcription factor) regulatory axis involved in the acquisition of a tumour-supportive phenotype by BV2 microglia once exposed to stimuli originating from C6 glioma cells." (PMID 39019900, 2024). "Other studies support the increase in ID1 and ID2 expression levels in H3K27-altered gliomas, either through mutations in ACVR1 and the upregulation of pSMAD1/5 in H3.1-altered gliomas or through other mechanisms in H3.3-altered gliomas." (PMID 39126064, 2024).
glioma (continued). "Supporting the idea of a pro-tumoral effect associated with ID2 expression, and inversely anti-tumoral property linked to ETS2 expression in GB tumours, high ID2 and ETS2 gene expression levels were found to be associated respectively with poor and good prognosis in cohort of patients with gliomas." (PMID 39019900, 2024). "Targeting ID2 with anti-ID2 siRNA increases sensitivity and decreases glioma apoptosis." (PMID 38002561, 2023). "Homozygous ID2 deletion in these cells resulted in decreased cell confluence, but no spontaneous differentiation, a phenotype that is consistent with the reported role for ID2 in maintaining glioma cancer cell stemness." (PMID 35149717, 2022). "This signal stabilizes Id2 expression that is crucial for glioma survival." (PMID 28122577, 2017). "Indeed recent studies in glioma have shown that ID2 can interfere with VHL activity in cell lines and that it’s subject to regulation by microRNAs." (PMID 29053101, 2017). "Likewise, our result suggests that ETS2 could exert similar functions in microglia, which could be repressed by the induction of ID2 expression in those cells when they are recruited and converted into tumour-trophic cells by the glioma cancer cells." (PMID 39019900, 2024). "A transient upregulation for both Id1 and Id2 messengers was validated in BV2 microglia, 2 h post segregated coculture with C6 glioma cells, when compared to BV2 microglia monoculture." (PMID 39019900, 2024). "Furthermore, ID2 and ETS2 gene expressions exhibited inverse prognostic values in patients with glioma in cohorts from The Cancer Genome Atlas." (PMID 39019900, 2024). "Furthermore, ID2 and ETS2 gene expressions exhibited inverse prognostic values for patients with glioma." (PMID 39019900, 2024). "High-grade glioma cells with high Id1 expression (but no Id2 and Id3 expression) show self-renewal capacity, whereas cells with low Id1 levels possess poor self-renewal capacity but proliferative potential." (PMID 28122577, 2017). "In gliomas, it has been reported that DYRK1A may destabilize HIF2-alpha in hypoxic conditions by phosphorylating thr27 of ID2, leading to reduced self-renewal of glioma stem cells, the inhibition of tumor growth, and more favorable outcomes for patients with glioblastoma." (PMID 31035417, 2019).
hepatocellular carcinoma (17 papers, 2013 to 2025). A malignant tumor that arises from hepatocytes. "Downregulation of inhibitor of DNA binding 2 (ID2) is associated with poor prognosis in cases of hepatocellular carcinoma (HCC)." (PMID 23403953, 2013). "BMP4-induced epithelial mesenchymal transition through upregulation of ID2 and promoted metastasis in hepatocellular carcinoma, which was associated with poor prognosis in patients with 420 paired HCC study." (PMID 37443106, 2023). "KIAA1429 inhibits ID2 by upregulating the m6A modification of ID2 mRNA in hepatocellular carcinoma, thereby promoting migration and invasion of hepatocellular carcinoma." (PMID 38585432, 2024). "To assess the role of Id2 in hepatoma development and progression, we administered DEN to Id2fl/flCd4-Cre− mice and Id2fl/flCd4-Cre+ mice on postnatal day 14 and monitored tumor development in the following 40 weeks." (PMID 38287103, 2024). "PRDX4 is overexpressed in a variety of tumor tissues, and inhibits anoikis resistance through the β-catenin/ID2 pathway, thereby promoting the growth and metastasis of hepatocellular carcinoma cells." (PMID 36092898, 2022). "In contrast, in a hepatocellular carcinoma, ID2 upregulation triggered invasion and metastasis via EMT induction." (PMID 35008299, 2021). "AC009495.2 suppresses tumour metastasis by activating the HDAC8/ID2 pathway in hepatocellular carcinoma." (PMID 32887470, 2020). "To determine whether loss of Id2 in T cells affects host antitumor immunity, we analyzed the role of Id2 in antitumor responses using melanoma, Lewis lung cancer and hepatoma models." (PMID 38287103, 2024). "Further investigation revealed that the β-catenin downstream gene ID2 is responsible for the oncogenic activity of PRDX4 in hepatocellular carcinoma (HCC) cells, promoting anchorage-independent growth and anoikis resistance." (PMID 41445793, 2025). "Researches indicate that the induction of EMT facilitated by ID2 promotes invasion and metastasis in hepatocellular carcinoma (HCC)." (PMID 38195969, 2024). "We hypothesize that increased ID2 may play a role because hepatocellular carcinoma (HCC) over-expressing ID2 showed decreased VEGF secretion." (PMID 39201703, 2024). "In hepatocellular carcinoma, KIAA1429 increased the m6A level of ID2 (a dominant-negative antagonist of transcription factors) mRNA, which subsequently reduced ID2 expression and promoted cell migration and invasion." (PMID 32258108, 2020). "In addition, one study of four genes [E‐cadherin, MMP9 (matrix metalloproteinase‐9), TCF3 (transcription factor 3)/E47 and ID2 (inhibitor of differentiation 2)] has validated their prognostic value, in terms of overall survival, in a large cohort of hepatocellular carcinomas (HCC)." (PMID 28590039, 2017).
colorectal cancer (16 papers, 2007 to 2025). A primary or metastatic malignant neoplasm that affects the colon or rectum. "Taken together, these data suggested that hypoxia-induced Wnt/β-catenin signaling was strongly associated with enhanced Id2 expression in colorectal cancer." (PMID 26965643, 2016). "Consistent with the qPCR data, the expression level of Id2 was significantly increased in colorectal-cancer cells under the hypoxic condition, suggesting that hypoxia was highly associated with enhanced Id2 expression in colorectal cancers." (PMID 26965643, 2016). "Furthermore, knockdown of Id2 expression not only inhibits proliferation but also induces apoptosis in colorectal cancer cells that have mutations in components of the Wnt signaling pathway." (PMID 26163528, 2015). "Furthermore, we investigated whether the up-regulation of Id2 expression was associated with the rate of apoptosis of colorectal-cancer cells." (PMID 26965643, 2016). "For example, butyrate enhances CD8+ T cell effector activity by upregulating inhibitor of DNA binding 2 (ID2) through HDACs inhibition, thereby markedly strengthening antitumor immunity in colorectal cancer models." (PMID 41357193, 2025). "Taken together, these data suggested that Wnt/β-catenin signaling mediated the hypoxia-induced self-renewal potential of colorectal-cancer CSCs through reactivating Id2 expression." (PMID 26965643, 2016). "The stimulatory effects of hypoxia on CSC-sphere formation were successfully attenuated by the Id2 knockdown in colorectal-cancer cells." (PMID 26965643, 2016). "After specifically filtering for the datasets of colorectal cancers showing tumor recurrence or metastasis, we observed significant correlations between upregulated Id2 expression and a higher incidence of colorectal-cancer recurrence or metastasis." (PMID 26965643, 2016). "To better understand the role of Id2 in colorectal cancers, we used shRNA to establish a stable Id2 knock-down cell line, and found that these cells had an increased rate of apoptosis and a reduced growth potential." (PMID 26965643, 2016). "We also investigated the roles of Id2 in the invasion and migration of colorectal-cancer cells using a transwell migration assay and a scratch assay." (PMID 26965643, 2016). "Through various in vitro studies, we found that hypoxia-induced Wnt/β-catenin signaling increased the occurrence of CSC-like phenotypes and the level of Id2 expression in colorectal-cancer cells." (PMID 26965643, 2016). "Id2-knockdown colorectal-cancer cells were subcutaneously injected into BALB/c mice, and tumor-cell metastasis/dissemination was monitored." (PMID 26965643, 2016). "The expression level of inhibitor of DNA binding 2 (Id2) is increased in colorectal carcinomas and is positively correlated with poor prognosis." (PMID 26163528, 2015). "High expression of ID2 has also been observed in colorectal cancer samples, and intraperitoneal injection of ID2 siRNA reduces the growth of colorectal tumors in mice, suggesting that ID2 could be a potential drug target for cancer treatment." (PMID 38195969, 2024). "Besides, ID2 was highly expressed in multiple cancers, including breast cancer, bladder cancer, pancreatic cancer, colorectal cancer and head and neck cancer." (PMID 32160589, 2020). "Consistent with this hypothesis, the stimulatory effects of hypoxia on CSC-sphere formation were successfully attenuated by knocking down Id2 expression in colorectal-cancer cells." (PMID 26965643, 2016). "Our data supported the finding of these prior studies related to the Id proteins and documented for the first time that Id2 regulated the self-renewal potential of CSCs and, furthermore, mediated the metastatic/dissemination potential of colorectal-cancer cells." (PMID 26965643, 2016). "Similarly, in the present study, the significant up-regulation of Id2 expression in colorectal-cancer cells after hypoxic exposure was demonstrated in vitro." (PMID 26965643, 2016).
colorectal cancer (continued). "Therefore, we examined the distribution of the actin cytoskeleton at the subcellular level in colorectal-cancer cells following the Id2 knockdown." (PMID 26965643, 2016). "To further investigate the potential role of hypoxia in Id2 expression and the regulatory role of Id2 in hypoxia-induced Wnt/β-catenin signaling in colorectal cancer, we analyzed the level of Id2 expression in the presence or absence of Wnt ligands under the hypoxic condition." (PMID 26965643, 2016). "Altogether, these results indicated that the Id2 expression level might be inversely correlated with colorectal cancer-cell survival." (PMID 26965643, 2016). "However increased expression of Id2 is observed in various human cancers including colorectal cancer, and often correlates with poor prognosis." (PMID 26163528, 2015). "Accordingly, regulation of BIM by ID2 has been also described in colorectal carcinoma." (PMID 20565746, 2010). "Among them, ID2 could enhance glioma and colorectal cancer formation." (PMID 32160589, 2020). "In addition to ID1 and ID3, ID2 expression is also induced in colorectal cancer cells by hypoxia." (PMID 29652830, 2018). "Therefore, to investigate whether Id2 depletion was sufficient to inhibit the hypoxia-induced CSC growth, we knocked down Id2 expression in colorectal-cancer cells using a specific shRNA." (PMID 26965643, 2016). "The upregulation of ID2 enhanced N-cadherin expression while suppressing E-cadherin leves, thereby participating in the EMT process and hepatic metastasis in colorectal cancer (CRC)." (PMID 38195969, 2024). "Importantly, knocking down ID2 expression reduced CD44 expression and tumor-sphere formation and reduced the metastatic potential of colorectal cancer cells in vivo." (PMID 29652830, 2018). "However, the precise mechanism by which Id2 regulates the survival or apoptosis of colorectal-cancer cells is not known, though many possibilities exist." (PMID 26965643, 2016). "We found that NCOR1, NONO, and PPP1CC were more highly expressed in right-sided colorectal cancer, while CLDN4, EGR1, and ID2 were more highly expressed in left-sided colorectal cancer." (PMID 41174721, 2025).
prostate carcinoma (16 papers, 2006 to 2024). A carcinoma that arises from epithelial cells of the prostate gland. "Of all the four Id proteins, the expression of Id1, Id2, and to a lesser extent, Id3 in prostate cancer and the underlying molecular mechanism is relatively well known." (PMID 23342267, 2012). "Moreover, in prostate carcinoma, strong ID2 expression was associated with poorly differentiated grades of tumor, suggesting that ID2 could also be involved in regulation of tumor dedifferentiation." (PMID 19129913, 2009). "To explore ID2 expression levels across different prostate cancer cell lines, we mined RNA-seq data from CCLE." (PMID 38254880, 2024). "Through cell function experiments and mouse experiments, we reveal that ID2 can promote prostate cancer evolution." (PMID 38254880, 2024). "ID2 can activate JAK/STAT signaling pathway as well as FGFR signaling pathway to promote the acquisition of prostate cancer lineage plasticity, which in turn leads to androgen receptor-negative prostate cancer." (PMID 38254880, 2024). "We transiently expressed ID2 in a panel of prostate cancer cell lines; Western blot analysis showed decreased expression of AR and PSA in LNCAP cells, while the expression of NE markers such as CHGA, ENO2, and SYP was elevated in both LNCAP and PC3 cells." (PMID 38254880, 2024). "Other studies have also reported that ID2 is upregulated in brain cancer, colon cancer, pancreatic cancer, and prostate cancer, in which it promotes tumor progression, making it an unfavorable prognostic factor." (PMID 33247706, 2020). "In prostate cancer the over-expression of B-cell leukemia 3 (Bcl3) protein is correlated with the expression of Id1 and Id2, which is in turn accompanied with resistance to pro-apoptotic drugs." (PMID 28122577, 2017). "In fact, Id-2 has also been shown to be upregulated in prostate cancer, whereas Id proteins have been shown to co-express and have redundant roles in some cellular contexts." (PMID 20010941, 2010). "For example, down-regulation of Id2 expression in highly metastatic PC-3 human prostate cancer cells reduced their growth potential and invasiveness, which indicates the pro-proliferation and pro-invasion roles of Id2 in some epithelial cancer cells." (PMID 19257909, 2009). "Our study indicates a potentially strong association between ID2 and the acquisition of a stem-like phenotype in adenocarcinoma cells, leading to resistance to androgen deprivation therapy (ADT) and next-generation ARPIs in prostate cancer." (PMID 38254880, 2024). "We found that ID2 expression was increased in AR-null prostate cancer." (PMID 38254880, 2024). "However, ID2 is upregulated in brain cancer, colon cancer, pancreatic cancer, and prostate cancer, in which it promotes tumor progression, making it an unfavorable prognostic factor." (PMID 29089860, 2017). "The expression of ID1, ID2, and at a lesser amount the ID3 genes were also investigated in several studies including prostate cancer researches and the relationship between their over-expression and cancer incidence was clearly perceived." (PMID 30876429, 2019). "In prostate cancer Bcl3 is overexpressed via IL6, leading to the up-regulation of Id1 and Id2, and inducing resistance against anticancer drugs." (PMID 28122577, 2017). "BMP4 has also been shown to inhibit growth of the prostate cancer cell line LNCaP and induce the expression of ID1, ID2, and ID3 in cell lines." (PMID 16638148, 2006).